OR4Q3 (olfactory receptor family 4 subfamily Q member 3)
Description:
Odorant receptor.
Synonyms: C14orf13; OR4Q4; HSA6; OR14-3; c14_5008
Gene: Protein-coding gene on chromosome 14 (19,743,571 to 19,749,469, forward strand). Ensembl gene ENSG00000182652.
Subcellular location: Cell membrane
Pathways (Reactome):
Sensory Perception: Expression and translocation of olfactory receptors; Olfactory Signaling Pathway
Genetic constraint (gnomAD): Loss-of-function variants: 15 observed, 15.48 expected, observed/expected ratio (o/e) 0.97, 90% interval 0.65 to 1.49. The upper end of that interval is the gene's LOEUF score, 1.49, which puts it in group 6 of 6, group 1 being the genes least tolerant of losing a copy. Missense variants: 371 observed, 321.72 expected, observed/expected ratio (o/e) 1.15, 90% interval 1.06 to 1.26. Synonymous variants: 149 observed, 121.62 expected, observed/expected ratio (o/e) 1.23, 90% interval 1.07 to 1.4.
Homologues: Orthologues: macaque OR4Q3 (93% identical), rabbit OR4Q3 (86% identical), dog OR4Q3B (84% identical), dog OR4Q3 (83% identical), mouse Or4q3 (79% identical), guinea pig OR4Q3 (77% identical), rat AC122990.1 (77% identical). Paralogues in human: OR4K14 (52% identical), OR4S2 (52% identical), OR4E1 (51% identical), OR4D1 (51% identical), OR4F5 (50% identical), OR4K15 (50% identical), OR4E2 (50% identical), OR4F4 (50% identical), OR4A15 (49% identical), OR4F17 (49% identical), OR4K13 (49% identical), OR4X2 (49% identical), and 116 more.
Diseases named in the same sentence as OR4Q3 in open-access papers:
OR4Q3 is named in the same sentence as 3 diseases in open-access papers, as found by Europe PMC text mining. Sharing a sentence is not in itself a finding about the gene and the disease. The quoted sentences say what the papers report.
glioblastoma (1 paper, 2025). The most malignant astrocytic tumor (WHO grade IV). "Although diseases associated with these genes have been reported less frequently, a recent study linked mutations in the OR4Q3 gene to glioblastoma." (PMID 41296379, 2025).
OR4Q3 also shares sentences with these, for which no sentence is quoted: breast carcinoma (1 paper); Down syndrome (1).